CXCR4 (C-X-C motif chemokine receptor 4)
Diseases named in the same sentence as CXCR4 in open-access papers (continued):
Sharing a sentence is not in itself a finding about the gene and the disease.
breast carcinoma (continued). "CXCR4 is one of the chemokine receptors that are critical for chemotherapy of metastatic cells, and treatment of MDA-MB-231 breast cancer cells with DHA reduced the surface expression of CXCR4 and reduced CXCR4-mediated cell migration." (PMID 40362847, 2025). "Studies have shown that CXCR4, which is highly expressed in breast cancer cells, is the only receptor for stromal cell-derived factor-1 (SDF-1)." (PMID 40308486, 2025). "Future studies should aim to explore these mechanisms in more detail, using functional assays to dissect how mercury bioaccumulation directly or indirectly influences CXCR4 expression and activity in breast cancer cells and their microenvironment." (PMID 40362664, 2025). "CCR7 has been shown to form heterodimers with CXCR4 in breast cancer cells resulting in a metastatic phenotype as well as allowing for increased survival in the absence of an extracellular matrix (ECM) attachment." (PMID 39982274, 2025). "Circ_0038632, highly expressed in breast cancer tissues, sponges miR-4306 to increase the expression of CXCR4 in breast cancer cells." (PMID 40710359, 2025). "It has recently emerged that CXCR4 is crucial for the survival, proliferation, migration, and metastasis of various cancers, including breast cancer." (PMID 40548301, 2025). "In another approach, Balixafortide (POL6326), a CXCR4 peptide antagonist, has also been successfully conjugated with a fluorescent probe to specifically detect breast cancer metastases in sentinel lymph nodes." (PMID 40307933, 2025). "Other work indicates that PA suppresses breast cancer cell invasion by downregulating the expression of CXC chemokine receptor 4 (CXCR4)." (PMID 40535769, 2025). "Remarkably, prior research has similarly suggested a positive correlation between CXCR4 expression levels and lymph node involvement in breast cancer." (PMID 40092486, 2025). "68Ga-Pentixafor uptake correlated significantly with HIV infection, underscoring the need to explore the potential synergistic effect of CXCR4 antagonists in HIV-infected breast cancer patients." (PMID 40075611, 2025). "Since the construct is intended to be used for the local treatment of breast cancer metastases in the bone niche, potential off-target effects on the CXCR4-expressing bone marrow must be considered." (PMID 41295054, 2025). "CXCR4 expression promotes breast cancer metastasis to organs where there is an abundance of its ligand, SDF-1/CXCL12, such as the lymph nodes, brain, skeleton/bone marrow, liver and lungs." (PMID 40075611, 2025). "Evaluation of RNAi efficiency following the delivery of anti-GFP or mock siRNA in CXCR4-positive breast cancer cells stably expressing eGFP gene revealed a marked difference between specific and control polyplexes." (PMID 41226635, 2025). "TGFβ1 upregulates CXCR4 expression in breast cancer cells and plays a prominent role in metastasis by enhancing angiogenesis and suppressing immune surveillance at secondary metastatic sites." (PMID 40075611, 2025). "CircFGFR4 prevents miR-185-5p from decreasing the expression of C-X-C motif chemokine receptor 4 (CXCR4) in breast cancer cells." (PMID 40710359, 2025). "In breast cancer stem cells, overexpression of miR-139 has shown to diminish stem cell homing and invasion by reducing CXCR4 levels." (PMID 40307933, 2025). "A recent study showed that CXCR4+ niche macrophages regulate the tumor-initiating activity of various breast cancer subtypes by enhancing TIC survival and tumor-forming capacity, while promoting early immune evasion through regulatory T cell induction." (PMID 41550427, 2025). "CXCL12 binds CXCR4 to direct metastatic homing of breast cancer cells to bone marrow, lungs, and liver; high CXCL12/CXCR4 axis activity is a hallmark of bone-tropic metastases." (PMID 41007766, 2025).
breast carcinoma (continued). "In various cancer models, including glioblastoma and HER-2 positive breast cancer, CXCR4 inhibition reduced tumor growth, invasion, metastasis, and stromal cell recruitment, highlighting its key role in tumor progression and the TME25,42,43." (PMID 41210695, 2025). "The aim of this prospective study was to establish the value of CXCR4-directed PET imaging in patients with breast cancer using the novel CXCR4-targeted PET probe 68Ga-Pentixafor by comparing it with 18F-FDG PET/CT (n = 40)." (PMID 40075611, 2025). "These CXCR4 antagonists have potential as anticancer drugs for the treatment of breast cancer because they prevent the CXCR4 receptor from attaching to its ligand, SDF-1, and therefore suppress tumor proliferation and metastasis." (PMID 40075611, 2025). "Expression levels of these genes were also examined across various pathological stages of breast cancer, where a stage-dependent increase was observed particularly for CXCR4, BMP1, VCAN, and WNT2." (PMID 41348904, 2025). "In a different approach, anti-CXCR4 antibodies were conjugated to gold nanoparticles aiming to enable tumor-selective radiotherapy in CXCR4+ breast cancer cells." (PMID 40307933, 2025). "bone-derived CXCL12 preferentially recruits breast cancer cells with high CXCR4 expression to bone metastasis sites." (PMID 40510151, 2025). "Breast cancer cells that exhibit an elevated expression of CXCR4 have a greater tendency to be attracted by CXCL12, which is secreted by osteoblasts and plays a role in attracting osteogenic precursors to bone marrow." (PMID 39980332, 2025). "Our findings in translational relevance open new avenues for using TGFβ-1 and CXCR4 as combinatorial therapeutic targets or prognostic markers, especially in the more aggressive subtypes of breast cancer." (PMID 41348904, 2025). "Dąbrowska examined the expression of CXCL12 and CXCR4 in 100 breast cancer patients, revealing that analyzing the expression levels of CXCL12/CXCR4 can enhance the accuracy of breast cancer diagnosis." (PMID 40607416, 2025). "In vivo, suppressing CXCL12/CXCR4 interactions drastically decreased breast cancer cell metastasis to the surrounding lymph nodes and lungs." (PMID 40548301, 2025). "Be it in the liver, lung, or bone the expression of the chemokine receptor CXCR4 promotes the spread of primary breast cancer cells to the secondary location and research has demonstrated that its silence inhibits metastasis." (PMID 41348904, 2025). "The seven amino acids long JM173 peptide should mediate the targeted delivery of the therapeutic cargo molecule C3bot1 toxin (indicated in this context as C3) into the cytosol of CXCR4 overexpressing breast carcinoma (BC) cells." (PMID 41295054, 2025). "•CXCR4 is the major downstream mediator negatively regulated by MEG3 that facilitates breast cancer cell migration." (PMID 40548301, 2025). "The CXCR4–CXCL12 axis has been extensively studied in breast-to-bone metastasis, where the pharmacological blockade of this pathway using the CXCR4 antagonist AMD3100 (Plerixafor) has been shown to reduce the migration of breast cancer stem cells to bone." (PMID 40362664, 2025). "When breast cancer cells express their cognate receptor, CXCR4, CXCL12 functions as a chemoattractant at secondary tumor locations, causing the cancer cells to migrate and homing." (PMID 41348904, 2025). "The CXC chemokine receptor 4, or CXCL12/CXCR4 axis, has been shown to contribute to the growth of primary breast carcinogenesis and is essential for the metastasis of breast cancer cells, which in turn leads to the establishment of secondary tumors." (PMID 41348904, 2025). "Chemokine receptor 4 (CXCR4) is a G protein-coupled receptor that is overexpressed in breast cancer cells but conserved in normal tissue cells." (PMID 40175784, 2025). "The ChIP assay conducted by the researchers demonstrated the ability of FOXC1 to bind to the CXCR4 promoter, thereby enhancing its fold enrichment in breast cancer." (PMID 40003882, 2025).
breast carcinoma (continued). "CXCR4 has been identified as a key regulator of metastasis in HER2 breast cancer, with studies indicating that its inhibition can have a favorable impact on prognosis." (PMID 39682150, 2024). "Chemokine receptor 4 (CXCR4) is highly expressed by breast cancer tissues, and its ligand, chemokine ligand 12 (CXCL12), is mainly in the lymph nodes." (PMID 39605887, 2024). "In order to clarify the expression of CXCR4 in different subtypes of breast cancer, we searched the samples from the cancer genome atlas (TCGA) database." (PMID 38774946, 2024). "In the context of cancer metastasis, the chemokine receptor CXCR4 has been observed to undergo upregulation and has been employed as a prognostic indicator in diverse cancer types, including leukemia, breast cancer, and PCa." (PMID 38628201, 2024). "In breast cancer tissues, dual positivity for CXCR4 and phosphorylated STAT3 (p-STAT3) correlates positively with tumor size, lymph node metastasis, and histological grade." (PMID 38920657, 2024). "CXCL12 interacts with CXCR4, a receptor expressed on breast cancer cells, to guide their migration toward high-CXCL12 areas." (PMID 39605887, 2024). "In breast cancer cells, AQP3 is associated with the induction of CXCL12/CXCR4-dependent cell migration, a critical process in breast cancer progression and metastasis." (PMID 39125952, 2024). "Validation studies have identified miR-139 as a direct regulator of CXCR4 in various cancers, including breast cancer." (PMID 39682150, 2024). "Antagonism through nanothread ‘patching’-induced CXCR4 superclusters profoundly amplifies the disruption of downstream signal cascade, seals the impetus of breast cancer cells for spontaneous metastasis, and constrains cancer cells within the primary tumor." (PMID 38553476, 2024). "Perivascular cells highly expressing CXCL12 in vascular microhabitats in bone marrow sinuses can keep breast cancer cells dormant in the vasculature through CXCL-12/CXCR4 interaction." (PMID 38464516, 2024). "Studies have shown that hypoxia induces CXCR4 expression in chondrosarcoma, breast cancer, and colon cancer." (PMID 39191749, 2024). "Among others, prostate and breast cancers preferentially metastasize to the bone and lungs via the CXCR4/CXCL12 axis, and approaches aimed at inhibiting this interaction have proven to significantly reduce metastatic spread." (PMID 38803493, 2024). "Breast cancer metastasis is promoted by multiple factors including notable contributors such as C-X-C chemokine receptor 4 (CXCR4 also known as CD184), Mouse Double Minute 2 (MDM2), and Mouse Double Minute 4 (MDM4 also known as MDMX)." (PMID 39766093, 2024). "In basal-like breast cancer, hypoxia increases CXCR4 expression in Tregs, enhancing their recruitment to the tumor site and suppressing the immune response." (PMID 39000453, 2024). "Accordingly, abundant CXCR4 expression is detectable on human breast cancer cells including MDA-MB-231 in contrast to normal human mammary epithelial cells." (PMID 39420354, 2024). "C-X-C motif chemokine receptor 4 (CXCR4) is a promising therapeutic target of breast cancer because it is overexpressed on cell surface of all molecular subtypes of breast cancer including triplenegative breast cancer (TNBC)." (PMID 38982161, 2024). "Similar to HER2, CXC chemokine receptor 4 (CXCR4) is commonly overexpressed by most breast cancers, making it an attractive targeting option for the treatment of breast cancers." (PMID 38893315, 2024). "It was also reported that high CXCR4 expression is correlated with poor clinical prognosis in breast cancer patients." (PMID 37760498, 2023). "One study showed that AGTR1 promotes lymph node metastasis and invasion in breast cancer by regulating CXCR4/SDF-1a." (PMID 36983741, 2023). "It was reported that the reduction in the gap junction and HIF1α and CXCR4 expression significantly inhibited the metastasis of breast cancer cells." (PMID 37511481, 2023).
breast carcinoma (continued). "An investigation on the SDF-1/CXCR4 axis in a breast carcinoma model revealed their role of hypoxia." (PMID 37056346, 2023). "In conclusion, we show here that DPP-4 inhibition accelerates breast cancer cell survival by inducing autophagy through CXCL12/CXCR4-mediated mTOR/HIF-1α activation; metformin abrogates such alterations induced by DPP-4 suppression." (PMID 37760498, 2023). "For example, we have shown previously that Grk3 overexpression in a line of metastatic breast cancer cells decreased CXCR4 internalization and increased cellular migration and metastasis in a mouse model of breast cancer." (PMID 37048054, 2023). "Nuclear expression of CXCR4 has been described in several solid tumor types including colorectal cancer, breast cancer, and prostate cancer." (PMID 36982302, 2023). "Our study, as the first, demonstrated that targeting CXCR4 synergizes with docetaxel in HER2 + breast cancer with trastuzumab resistance." (PMID 37280713, 2023). "Here, we show that HRH1 is widely expressed in various cancer cell lines and cancer tissues and that coexpression of CXCR4 and HRH1 is associated with poor prognosis in breast cancer." (PMID 36732336, 2023). "Accordingly, neutralizing the interactions of CXCL12/CXCR4 impaired metastasis of breast cancer cells to regional lymph nodes and lung." (PMID 37490147, 2023). "It was recently suggested that knockdown of CXCR4 (with RNA interference or pharmacological inhibition with AMD3100) substantially limited orthotopic growth of breast cancer cells in vivo and prevented the development of macroscopically detectable metastases." (PMID 36882818, 2023). "Teams from different countries using different methods showed CXCR4 upregulation in breast cancer with trastuzumab resistance." (PMID 37280713, 2023). "The present study provided preclinical evidence that targeting CXCR4 abrogates trastuzumab resistance by blocking cell cycle progression and synergizes with docetaxel in trastuzumab-resistant breast cancer treatment." (PMID 37280713, 2023). "An example of a selective CXCR4 antagonist is balixafortide, which has been shown to enhance the cytotoxic effect of chemotherapy in breast cancer." (PMID 39355052, 2023). "It was confirmed that in a hypoxic tumor niche activation of HIF leads to the transcription of an array of HIF target genes including SDF-1 and CXCR4 which contributes to tumor cell migration and adhesion to endothelial cells in breast cancer cells." (PMID 37056346, 2023). "Taken together, these findings showed that CXCR4 plays a role in primary resistance to trastuzumab in HER2 + breast cancer, and combined targeting of CXCR4 sensitizes the tumor cells to trastuzumab." (PMID 37280713, 2023). "CXCL12 can increase the migration and proliferation of stromal cells in breast cancer by recruiting CXCR4, which is related to breast cancer cell lymph node metastasis." (PMID 36755259, 2023). "To confirm that CXCR4 contributes to trastuzumab resistance, we analyzed CXCR4 protein expression in a panel of HER2 + human breast cancer cell lines that were confirmed with different sensitivities to trastuzumab." (PMID 37280713, 2023). "Specifically, CXCR4 mainly mediated breast cancer invasion, while CXCR7 inhibited invasion but promoted primary breast tumor growth through angiogenesis." (PMID 37497001, 2023). "Breast cancer metastasis to the lungs was the first tissue in which the CXCR4, a 352-amino-acid rhodopsin-like GPCR, was identified." (PMID 37629071, 2023). "CXCR4-expressing breast cancer cells stably expressed histone 2B fused to mCherry (H2B-mCherry) and independent Akt and ERK kinase translocation reporters (KTRs)." (PMID 36829763, 2023). "For example, in breast cancer, CXCR4 was found in both the cytoplasm and nuclei of tumor cells, but only the cytoplasmic expression was linked to lymph node metastasis." (PMID 37444550, 2023).
breast carcinoma (continued). "A few preclinical studies have demonstrated the ability of CXCR4-targeted therapies to inhibit cancer progression and metastasis in breast cancer." (PMID 36832085, 2023). "CXCR4 is downregulated in dormant breast cancer cells in the lungs, and the upregulation of CXCR4 with its ligand, CXCL12, promotes AKT signaling and proliferation." (PMID 37440925, 2023). "Our findings identify a novel role for DPP-4 inhibition in the promotion of breast cancer survival by inducing CXCL12/CXCR4/mTOR/HIF-1α axis-dependent autophagy." (PMID 37760498, 2023). "Tissue immunofluorescence staining was performed to investigate the distribution of these markers such as En_CXCR4, En_PPP1R1B, and En_S100A9 in breast cancer tissues and the relationship with the position distribution of blood vessels." (PMID 37626402, 2023). "NF-κB stimulates the expression of the chemokine receptor CXCR4 to encourage the migration and metastasis of breast cancer cells." (PMID 37025405, 2023). "The nuclear factor kappa B (NF-κB) signaling pathway is downstream of CXCL12/CXCR4, modulating breast cancer progression along with inflammation, cell proliferation, migration, and invasion." (PMID 38004606, 2023). "Other mechanosensors promoting EMT via several pathways such as transient receptor potential melastatin 7 (TRPM7)/SOX4 in breast cancer, CXCR4/ubiquitin domain containing 1 (UBTD1)/YAP in hepatoma and EGFR in glioblastoma have been reported." (PMID 36906534, 2023). "To examine the cellular and subcellular distribution of CXCR4 expression in HER2 + breast cancer residual tissues, we performed immunohistochemical staining and confirmed CXCR4 expression in tumor cells." (PMID 37280713, 2023). "CXCR4 is a G protein-coupled chemokine receptor which has a very well-known role in breast cancer proliferation and metastasis." (PMID 37550554, 2023). "Activating CXCR4 signaling by SDF-1 causes mammosphere development and resistance to anoikis in breast cancer cells." (PMID 36675306, 2023). "CXCR4 is responsible for breast cancer metastasis to organs such as lung, liver, lymph nodes, and bones, which express higher levels of CXCL12." (PMID 37749552, 2023). "Zerumbone, a component of subtropical ginger (Zingiber zerumbet), is a novel CXCR4 expression inhibitor that reduced CXCR4 expression in breast cancer by down-regulating NF-κB signaling." (PMID 37497001, 2023). "Breast cancer cells on 350-kPa hydrogels exhibit a higher unbinding force of a GPCR family member CXCR4 than normal mammary cells." (PMID 37864030, 2023). "In breast cancer, WWP1 negatively regulates CXCL12-induced CXCR4 lysosomal degradation, thereby facilitating breast cancer cell migration and bone metastasis, leading to poor prognosis (Fig. 5C1,)." (PMID 38129384, 2023). "Tao Zhu and colleagues reported that ETV4 promotes breast cancer cell stemness by activating glycolysis and CXCR4-mediated sonic hedgehog signaling." (PMID 37205199, 2023). "To confirm that CXCR4 plays a role in acquired trastuzumab resistance, we re-created trastuzumab-resistant breast cancer models via continuous exposure of the trastuzumab-sensitive cells to trastuzumab (20 μg/ml) for at least 1 year." (PMID 37280713, 2023). "Contradicting studies have shown either an overexpression and a dowregulation or CXCR4 in breast cancer bone metastasis, both pointing to a proliferative role of the CXCL12/CXCR4 axis." (PMID 37182144, 2023). "AGTR1 promotes breast cancer lymph node metastasis by increasing the chemokine CXCR4/SDF-1α and tumor cell migration and invasion." (PMID 36983741, 2023). "Bone marrow endothelial cells express CXCL12 and mediate adhesion and recruitment of breast cancer cells that express CXCR4." (PMID 38041134, 2023). "For colorectal as well as breast cancer, meta-analyses also confirmed poor prognosis for patients with strong CXCR4 expression." (PMID 36672341, 2023).